TIGIT (T cell immunoreceptor with Ig and ITIM domains)
Diseases named in the same sentence as TIGIT in open-access papers (continued):
Sharing a sentence is not in itself a finding about the gene and the disease.
tumor (continued). "NK and CD8+ T-cell functions were suppressed by TIGIT-intrinsic expression, thereby helping tumor (colorectal) growth in vivo." (PMID 32117298, 2020). "Several therapies have also been described that target the CD155/TIGIT axis in other tumor types, primarily utilizing checkpoint inhibitors and often targeting one or multiple other ligands in combination with CD155/TIGIT." (PMID 32532329, 2020). "To elucidate the mechanism of action of antagonist TIGIT antibodies in anti-tumor responses, we generated a series of rat anti-mouse TIGIT antibodies based on in vitro binding and blocking assays [mTIGIT:mouse CD155 (mCD155) interaction]." (PMID 33117369, 2020). "Among these inhibitory receptors, TIGIT on NK cells can mainly contribute to NK cell exhaustion in tumor-bearing mice." (PMID 32403291, 2020). "One possibility is that anti-TIGIT blockade provides complementary anti-tumor activities to the IFN-γ pathway by reinforcing the granzyme B and perforin activations." (PMID 33117369, 2020). "In patients with cancer, TIGIT and CD96 are upregulated in tumor-associated NK cells and promote NK cell functional exhaustion, accompanied by poor cytolytic potential and impaired cytokine production." (PMID 32140153, 2020). "In preclinical models, anti-TIGIT antibodies have been shown to be efficacious in driving anti-tumor efficacy." (PMID 33117369, 2020). "The observed anti-tumor activity is far reduced when using the same anti-TIGIT antibodies but with an isotype devoid FcγR engagement." (PMID 33117369, 2020). "PVR and Nectin-2 are expressed by tumor cells as well as myeloid cells, while TIGIT, CD96, and DNAM-1 are expressed on effector lymphoid cells." (PMID 32489646, 2020). "Here we have explored the role and requirement for IgG-Fc:FcγR interactions in addition to antagonism of TIGIT:CD155 binding in preclinical tumor models using anti-TIGIT antibodies as therapeutic agents." (PMID 33117369, 2020). "TIGIT blockade reversed NK dysfunction with superior anti-tumor effects in multiple murine tumor models." (PMID 32117816, 2020). "Again, the most frequent immune targets in CD4+ T cells from patients with GBM, in descending order, isolated from the tumor microenvironment were A2aR > PD-1 > CTLA-4 > CD39 > TIGIT > FOXP3 > LAG-3 > CD160 > TIM3 > KIR > CD73." (PMID 32721947, 2020). "Recent research has found that TIGIT upregulation can be inhibited by Tox- deletion in tumor-specific T cells." (PMID 33490104, 2020). "The Fap2 protein expressed on FN directly binds TIGIT on NK cells in colon adenocarcinoma tumors, reducing NK cell activity and enabling tumor evasion." (PMID 32153582, 2020). "With its ligand, poliovirus receptor, the role of TIGIT in the tumor immune environment resembles the PD-1/PD-L1 interaction in tumor immunosuppression." (PMID 35582437, 2020). "The novel immune checkpoint TIGIT/PVR plays critical roles in suppressing the anti-tumor effects of CD8+ T and NK cells, and dual blockade of TIGIT/PVR and PD-1/PD-L1 by antibody can elicit synergistic effects in tumor models and clinical trials." (PMID 32894141, 2020). "In this study, we found that TIGIT was highly expressed in tumor tissues and that high TIGIT expression predicted a more advanced disease stage and worse prognosis in PSCCE." (PMID 33490104, 2020). "Tumor-bearing mice were treated with anti-PD-1:mIgG1*, anti-TIGIT:mIgG1*, anti-TIGIT:mIgG2a, or isotype control antibodies through two treatment cycles 4 days apart." (PMID 33117369, 2020). "We next set out to investigate this alternative FcγR-dependent mechanism of tumor growth inhibition by anti-TIGIT antibody treatment." (PMID 33117369, 2020). "CD155 and CD112 have been linked to tumor progression and migration in primary tumors and have also been shown to have an immunomodulatory role through interaction with DNAM-1, TIGIT, and CD96 on NK cells." (PMID 32532329, 2020).
tumor (continued). "As a checkpoint, receptor blockade of TIGIT prevented NK cell dysfunction and elicited NK cell anti-tumor responses in tumor-bearing mouse models." (PMID 31234517, 2019). "Before tumor appearance, TIGIT maintains hepatic immune tolerance and induces CD8+ T cell dysfunction in HBV transgenic mice, thereby inhibiting immune-mediated injury and delaying tumor initiation." (PMID 30644386, 2019). "In particular, genetic KO or mAb-mediated blockade of TIGIT was able to unleash both NK cell and T cell antitumor activity, leading to a substantial improvement in the control of tumor growth in several preclinical mouse models." (PMID 31105707, 2019). "In humans, TIGIT is constitutively expressed by NK cells, which was up-regulated on NK cells in tumor regions compared with NK cells from peri-tumoral regions." (PMID 31552017, 2019). "Consistently, CD103+ tumor resident NK cells displayed higher expression of TIGIT than CD103− circulating NK cells." (PMID 31552017, 2019). "Here, we found that TIGIT and Poliovirus receptor (PVR, CD155) are expressed in tumour cells; the TIGIT and CD155 protein expression in cancer tissue has been found to be significantly higher than that in the precancerous tissue." (PMID 31090213, 2019). "In tumor-bearing mice or in patients with colorectal cancer, blocking TIGIT prevented the exhaustion of NK cells and enhanced NK cell-mediate tumor immunity." (PMID 31340613, 2019). "Blockade of IDO and TIGIT with monoclonal antibodies increases the proportion of antitumoral T cells and delays tumor growth in vitro." (PMID 30993893, 2019). "Recently, additional inhibitory checkpoints (such as PD-1, TIGIT, etc.), which under normal conditions maintain immune cell homeostasis, have been shown to facilitate tumor escape." (PMID 31105707, 2019). "Antibody blockade of TIGIT and the PD-1/PD-L1 axis enhanced tumour cell clearance by CD8+ T cells and significantly prolonged control of myeloma in a mouse model of autologous stem cell transplantation." (PMID 30626155, 2019). "Mean tumor volume at day 39 was significantly lower in the 18x2Gy + anti-PD-L1 group (p = 0.01) and 18x2Gy + anti-PD-L1 + anti-TIGIT group (p = 0.04) compared to the 18x2Gy group." (PMID 31238970, 2019). "TIGIT is also upregulated in tumor specific TILs and dual blockade with anti-PD-1 enhanced anti-tumor immunity." (PMID 30621125, 2019). "Whereas DNAM-1 is an activating/co-stimulatory receptor involved in recognition and lysis of tumor cells, TIGIT and PVRIG engagement inhibit NK cell function." (PMID 31234588, 2019). "TIGIT expression on naïve T cells is usually low, though it is upregulated following activation, and particularly on exhausted T cells in the tumor microenvironment (TME)." (PMID 31500665, 2019). "These cells however overexpressed immune checkpoint inhibitory molecules, such as PD1, BTLA, TNFSF14 (LIGHT), and TIGIT, which are the sign of immune exhaustion or inhibition of tumor infiltrating lymphocytes." (PMID 30965637, 2019). "The blockade of TIGIT via mAbs reversed the exhaustion of anti-tumor NK cells in multiple tumor models, enhanced the infiltration of activated (CD69+) NK cells into tumors and thereafter improved the OS of the host." (PMID 30805309, 2019). "The DNAM-1 activating receptor and the TIGIT/PVRIG/TACTILE inhibitory axis have been shown to be key regulators of anti-tumor immune responses." (PMID 31234588, 2019). "In mouse models and on-going clinical studies, blockade or ablation of TIGIT, alone or in combination with blockade of PD-1, can restore tumour suppressive effects." (PMID 30733837, 2019). "In humans, the constitutive expression of TIGIT on NK cells was further up-regulated in tumor regions compared with peritumoral regions in colorectal tumors." (PMID 31552017, 2019). "The expression of checkpoint inhibitory receptor TIGIT on NK cells was up-regulated along tumor progression in mice." (PMID 31552017, 2019).
tumor (continued). "In the CT26 cancer model, Fc with effector functions is critical for TIGIT antibody-mediated anti-tumor activity." (PMID 30863404, 2019). "Mean tumor volume at day 39 was lowest in the 3x8Gy + anti-PD-L1 + anti-TIGIT group (p < 0.05) compared to all the other 3x8Gy groups." (PMID 31238970, 2019). "TIGIT deficiency in NK cells alone has been reported to be sufficient to delay tumor growth in multiple tumor-bearing mouse models, and anti-TIGIT mAbs reverse NK cell exhaustion." (PMID 32039024, 2019). "In vitro TIGIT blockade improves the anti-tumor effect of Trastuzumab (a recombinant humanized anti-HER2 mAb), which partially relies on NK cell-mediated ADCC." (PMID 30805309, 2019). "Tumour‐associated Treg cells are known to express numerous co‐stimulatory (i.e. ICOS, OX40, GITR) and co‐inhibitory (i.e. Lag‐3, Klrg1, Tim‐3, TIGIT, PD‐1) receptors that modulate their function." (PMID 31032905, 2019). "Here we show that expression of TIGIT, a promising immune checkpoint in tumor immunotherapy, increases with age on hepatic CD8+ T cells in HBsAg-transgenic (HBs-tg) mice whose adaptive immune system is tolerant to HBsAg." (PMID 30644386, 2019). "Ex vivo combinational antibody blockade of TIGIT and PD-L1 enhanced anti-tumour immunity, restored viral-specific CD8+ T cells, and reinvigorated the CD4+ T cell response." (PMID 31337800, 2019). "Like PD-1, TIGIT is expressed on both T and NK cells and suppresses anti-tumor effector function in both." (PMID 31456796, 2019). "In tumour and chronic infection mouse models, the essential role of TIGIT (T cell immunoglobulin and immunoreceptor tyrosine-based inhibitory motif [ITIM] domain) as a regulator of the anti-tumour and anti-viral CD8+ T cell response has been demonstrated." (PMID 31337800, 2019). "Blockade of TIGIT with α-TIGIT significantly increased the CD8+ T cells infiltration into the tumor." (PMID 30555485, 2018). "By plotting TIGIT expression in tumor and adjacent normal tissues, respectively, we found that TIGIT was overexpressed in tumors compared to normal tissues (tumor vs. normal, p < 0.001)." (PMID 30555485, 2018). "Together, these results provide possibility that tumor cells exert immunosuppressive role on NK and CD8+ T cells through the interaction of tumor-TIGIT and immune cells-PVR." (PMID 30555485, 2018). "Similar tumor inhibition along with a higher production of IFN-γ by tumor-infiltrating T cells were seen in C57BL/6 mice bearing TIGIT knockout MC38 cells." (PMID 30555485, 2018). "Here we report discovery of a novel, humanized, Fc-enabled, subnanomolar anti-TIGIT antibody with significantly enhanced tumor inhibition as a monotherapy, thus differentiating it from current anti-TIGIT molecules." (PMID 30400822, 2018). "Further, we established BABL/c nude and CD8+ T cells depleting model to verify the role of CD8+ T cells in the process of tumor inhibition by TIGIT knockout." (PMID 30555485, 2018). "Data assembled from TCGA identified tumor types in which expression of TIGIT is greater than PD-1, equivalent to PD-1, or expressed at low levels." (PMID 30400822, 2018). "In summary, the results of our study identify HL as a tumor type with frequent but variable expression of immune checkpoint receptors such as TIGIT and PD-1." (PMID 30514251, 2018). "These functions are absolutely different from the effects of TIGIT on T cells in transmitting inhibitory signal and mediating tumor evasion through the ITIM motif by ligation with PVR." (PMID 30555485, 2018). "Fap2, when bound to the human inhibitory receptor, TIGIT, inhibits the cytotoxic activity of natural killer (NK) cells against cancer cells, thus, allowing proliferation of the latter eventually leading to tumor growth." (PMID 29619076, 2018). "The CD226 receptor, which competes with TIGIT for the same ligands, can promote the cytotoxic and anti-tumor responses of mouse NK cells." (PMID 30364127, 2018).
tumor (continued). "Combined blockade of TIGIT and PD-1 also resulted in significant tumor clearance via enhanced CD8+ T cell effector function." (PMID 30250471, 2018). "Conversely, levels of TIGIT are elevated in chronic infectious diseases and cancers, and negatively regulate anti-infection and anti-tumor responses." (PMID 30364127, 2018). "In mouse models and ongoing clinical studies, blockade or ablation of TIGIT, alone or in combination with blockade of programmed cell death protein (PD-1), can restore tumor suppressive effects." (PMID 30514251, 2018). "TIGIT is upregulated on tumor antigen-specific CD8+ T cells and CD8+ tumor-infiltrating lymphocytes in various cancer types and TIGIT receptor/poliovirus receptor (PVR) ligand interaction signaling inhibits cytotoxicity mediated by NK and CD8+ T cells." (PMID 30400822, 2018). "To check the DNA epigenetic modifications in immune checkpoints/ligand in the breast TME, we examined the promoter CpG methylation profile of genes including PD-1, CTLA-4, TIM-3, LAG-3, PD-L1, and TIGIT in tumor and normal tissues." (PMID 29983831, 2018). "TIGIT is also upregulated on tumour antigen-specific CD8+ T cells and CD8+ tumour-infiltrating lymphocytes (TILs) from patients with melanoma." (PMID 29996914, 2018). "In vivo, two different isotypes of a surrogate mouse anti-TIGIT mAb were used to evaluate the anti-tumor efficacy in the colon carcinoma CT26 syngeneic murine model." (PMID 30400822, 2018). "Anti-TIGIT demonstrates preclinical in-vivo anti-tumor effects as a single agent and with anti-PD-1." (PMID 30400835, 2018). "Another checkpoint molecule, T cell immunoglobulin and immunoreceptor tyrosine-based inhibitory motif domain (TIGIT) was recently found to be highly expressed on the exhausted tumor-infiltrating NK cells." (PMID 30463262, 2018). "Here, our study updates the current knowledge of the immune checkpoint TIGIT in several aspects and identifies the vital role of TIGIT in tumor cells." (PMID 30555485, 2018). "We therefore propose a novel TIGIT/PVR interaction mode that tumor intrinsic TIGIT delivers inhibitory signals to CD8+ T cells and NK cells by engaging with PVR." (PMID 30555485, 2018). "Using a library of F. nucleatum mutants, the authors identified Fap2 as the bacterial protein that directly interacted with TIGIT, leading to inhibition of NK cytotoxicity and downregulation tumor-infiltrating T lymphocytes activation." (PMID 28321417, 2017). "The TIGIT-deficient mice showed significantly delayed tumor progression in different tumor models, suggesting that TIGIT negatively regulates antitumor responses." (PMID 28545567, 2017). "Faq2 protein of Fusobacterium nucleatum, bacteria present in the tumor microenvironment, is a ligand for inhibitory receptor TIGIT." (PMID 28702032, 2017). "Faq2 was found able to bind to tumor cells and to mediate inhibition of NK cell activity by triggering TIGIT signaling." (PMID 28702032, 2017). "LAG-3 is highly co-expressed with other immune inhibitory molecules, including TIM-3, PD-1, 2B4 and T-cell immunoglobulin and ITIM domain (TIGIT), on tumor-specific CD4+ effector T cells." (PMID 28404974, 2017). "In mouse cancer models, in contrast to minimal effects of blockade of TIGIT or PD-L1 alone, combined blockade of TIGIT and PD-L1 can induce substantial tumor regression and improved survival by enhancing the function of CD8+ TILs." (PMID 28443090, 2017). "In fact, a core set of inhibitory receptors, including PD-1, LAG-3,Tim-3, and the T cell immunoglobulin and ITIM domain (TIGIT, also known as Vstm3 and WUCAM), is also expressed on tumor-infiltrating lymphocytes (TILs)." (PMID 28545567, 2017). "Another immune checkpoint that has exciting potential for tumor immunotherapy is TIGIT (T cell immunoreceptor with immunoglobulin and ITIM domain)." (PMID 29276510, 2017). "This study suggests a new therapeutic strategy for ATL patients: the co-blockade of TIGIT and PD-1 to restore anti-tumor and anti-virus immune responses." (PMID 26735971, 2016).
tumor (continued). "RORγ agonists also attenuate immunosuppressive mechanisms by curtailing Treg formation, diminishing CD39 and CD73 expression, and decreasing levels of co-inhibitory receptors including PD-1 and TIGIT on tumor-reactive lymphocytes." (PMID 28123897, 2016). "In particular, a number of inhibitory pathways play a critical role in impeding T cell responses to tumor antigens, including PD-1, Tim-3 and TIGIT." (PMID 27461275, 2016). "Meanwhile, the expression levels of PD-1, TIM-3 and TIGIT were significantly higher in tumor-infiltrating lymphocytes (TILs) than that in peripheral T cells in the cancer patients." (PMID 27577071, 2016). "The TIGIT:CD3 ratio is increased on T cells in multiple human tumors compared to the corresponding normal tissues indicating that TIGIT is specifically upregulated in tumor-infiltrating T cells." (PMID 26347741, 2015). "Whereas PD-L1 or TIGIT blockade alone have little effect, PD-L1 and TIGIT co-blockade dramatically improves CD8-mediated control of tumor growth leading to complete rejection in the majority of mice." (PMID 26347741, 2015). "Together, these findings support tumor-wide upregulation of the TIGIT/CD155 axis in CRC and suggest that TIGIT, more than CD155, tracks with MSI/BRAF-associated immune activation, providing a rationale for patient stratification in checkpoint-directed immunotherapy." (PMID 41596586, 2026). "Furthermore, the deletion of Lkb1 increased the expression of inhibitory receptors PD-1 and TIGIT, further impairing NK cell-mediated tumor surveillance." (PMID 41896546, 2026). "In our study, we observed increased TIGIT protein levels in BRAF-mutated tumor group compared with the BRAF wild-type CRC tumor group, whereas no similar association was found for CD155 concentrations." (PMID 41596586, 2026). "In particular, KRAS mutation has been linked to shifts in the composition and functional state of tumor-infiltrating immune cells rather than to a uniform increase or decrease in global TIGIT/CD155 expression across the entire tissue." (PMID 41596586, 2026). "Moreover, the abundance of the repressive histone mark H3K9me3 in the promoter regions of TIGIT was significantly lower in CRC tumors compared with non-tumor tissues." (PMID 41596586, 2026). "Such a disturbed epigenetic landscape may favor both the silencing of tumor suppressor genes and the derepression of immune-regulatory genes, including TIGIT." (PMID 41596586, 2026). "Furthermore, 9-ING-41 (Elraglusib), a GSK-3β inhibitor, indirectly blocks TIGIT signaling while enhancing cytokine production and tumor regression." (PMID 41486149, 2026). "Thus, future studies should explore biomarkers that represent TIGIT/PVR signaling activity in tumor tissues along with PD-L1 expression levels." (PMID 39847233, 2025). "Notably, bioluminescence imaging revealed a significant reduction in tumour volume after anti-PD-1 plus anti-TIGIT antibody treatment on Day 21 and Day 30 compared to the controls treated with PBS." (PMID 39939955, 2025). "Additionally, analysis of tumor biopsies using advanced digital pathology tools revealed a high expression not only of inhibitory receptors such as PD-1 and TIGIT, but also of PD-L1, indicating a strongly immunosuppressive microenvironment." (PMID 41300994, 2025). "In contrast, the CXCL13-CD8+PD-1+TIGIT+ T cells exhibit features indicative of terminal exhaustion phenotypes, including diminished functional capacity and reduced responsiveness to tumor antigens, aligning more closely with terminally exhausted CD8+ Tex cells." (PMID 40799645, 2025). "Future research should focus on unravelling mechanisms of primary and adaptive resistance, optimizing combination regimens, and stratifying patients based on CD226 expression, PD-L1 levels, and tumor immune contexture to fully harness the therapeutic potential of TIGIT inhibition." (PMID 41303538, 2025).